RPSAP52 (ribosomal protein SA pseudogene 52 )
Synonyms: RPSA_17_1251
Gene: Long non-coding RNA gene on chromosome 12 (65,728,513 to 65,826,997, reverse strand). Ensembl gene ENSG00000293176.
Diseases named in the same sentence as RPSAP52 in open-access papers:
RPSAP52 is named in the same sentence as 21 diseases in open-access papers, as found by Europe PMC text mining. Sharing a sentence is not in itself a finding about the gene and the disease. The quoted sentences say what the papers report.
gastric cancer (3 papers, 2022 to 2024). A primary or metastatic malignant neoplasm involving the stomach. "Since STAT3 can regulate the expression of multiple genes that promote proliferation, anti-apoptosis, angiogenesis, and immune escape in gastric cancer cells, presence of lncRNA RPSAP52 enhances the malignant features of gastric cancer." (PMID 37894282, 2023). "In line with this conclusion, our results demonstrated that depletion of lncRNA RPSAP52 resulted in elevation of cell apoptosis and lncRNA RPSAP52 acted as an oncogene in gastric cancer." (PMID 35322746, 2022). "The results of this study showed that lncRNA RPSAP52 was elevated dramatically in gastric cancer cells and lncRNA RPSAP52 depletion was found to exert anticancer effects in gastric cancer via regulating miR-665/STAT3." (PMID 35322746, 2022). "Remarkably, STAT3 depletion, lncRNA RPSAP52 depletion and miR-665 overexpression functions equally in gastric cancer." (PMID 35322746, 2022). "We concluded that depletion of lncRNA RPSAP52 functions in gastric cancer via up-regulating miR-665." (PMID 35322746, 2022). "This study aimed to investigate the mechanism of lncRNA RPSAP52-mediated miR-665/STAT3 signaling pathway in gastric cancer, and to propose new targets for the treatment of gastric cancer." (PMID 35322746, 2022). "The consistent results were found in vivo and in vitro, denoting that lncRNA RPSAP52 is a critical regulator of great clinical potential in gastric cancer." (PMID 35322746, 2022). "Remarkably, the effects of miR-665 overexpression were in agreement with the impacts of depletion of lncRNA RPSAP52 in gastric cancer cells." (PMID 35322746, 2022). "Obviously, lncRNA RPSAP52 depletion and miR-665 overexpression function identically in gastric cancer, supporting that lncRNA RPSAP52 depletion functions via elevation of miR-665." (PMID 35322746, 2022). "The results showed that lncRNA RPSAP52 was significantly upregulated in four gastric cancer cell lines, among which the up-regulation fold was higher in MKN-28 and SGC-7901 cells, so these two cell lines were selected for subsequent experiments." (PMID 35322746, 2022). "We further assessed the level of lncRNA RPSAP52 in five types of gastric cancer cells and lncRNA RPSAP52 was found to be drastically upregulated in MKN-28 and SGC-7901 cells." (PMID 35322746, 2022). "Chao He and colleagues investigated the link between the lncRNA RPSAP52 and different types of cancer and reported that its depletion prevents cell proliferation and triggers cell cycle arrest at the G0-G1 checkpoint in gastric cancer (GC) cells while accelerating their apoptosis." (PMID 39309860, 2024). "Accordingly, we further examined whether the effects of STAT3 depletion was in accordance with the effects of lncRNA RPSAP52 depletion and miR-665 mimics in gastric cancer cells." (PMID 35322746, 2022). "Given the important role of lncRNA RPSAP52 in multiple cancers, we hypothesized that it also promotes the oncogenic function of gastric cancer cells." (PMID 35322746, 2022). "In this study, we identified a new regulatory axis lncRNA RPSAP52/miR-665/STAT3 in gastric cancer." (PMID 35322746, 2022). "LncRNA RPSAP52 is a newly identified functional molecular in several cancers, but its role in gastric cancer (GC) is currently unclear." (PMID 35322746, 2022). "Taken together, the effects of STAT3 depletion on cell proliferation, apoptosis and cell cycle are consistent with LncRNA RPSAP52 depletion and mir-665 overexpression in gastric cancer cells, suggesting that STAT3 is downstream target of the LncRNA RPSAP52/mir-665 axis target gene." (PMID 35322746, 2022).
glioblastoma (3 papers, 2021 to 2026). The most malignant astrocytic tumor (WHO grade IV). "LncRNA RPSAP52, a newly discovered lncRNA, has been reported to engage in several kinds of cancer including tongue squamous cell cancers, glioblastoma, and pituitary tumor." (PMID 35322746, 2022). "Recently, a new lncRNA RPSAP52 has been identified and revealed to participate in several tumours such as glioblastoma, pituitary tumours and pancreatic cancer." (PMID 33787061, 2021). "Wang et al33 showed that RPSAP52 predicted postoperative survival and promoted cell stemness in glioblastoma through regulating TGF‐β1." (PMID 33787061, 2021). "LncRNA RPSAP52 has been confirmed as an oncogene in glioblastoma." (PMID 35322746, 2022). "Finally, RPSAP52 may be a potential therapeutic target for glioblastoma given its positive regulatory function on TGF-β1." (PMID 41431719, 2026).
pituitary tumor (3 papers, 2020 to 2023). A benign or malignant neoplasm affecting the pituitary gland. "Lnc RPSAP52: Lnc-RNA RPSAP52 is in the cytoplasm and was discovered to be related to pituitary tumors." (PMID 37762249, 2023). "Previous study demonstrates that lncRNA RPSAP52 accelerates cell proliferation via regulating cell cycle in pituitary tumor." (PMID 35322746, 2022). "LncRNA RPSAP52 is found to upregulate HMGA2 via functioning as sponges of miR-16, miR-15b, and miR-15a in pituitary tumor." (PMID 35322746, 2022).
Ewing sarcoma (2 papers, 2019 to 2021). A small round cell tumor that lacks morphologic, immunohistochemical, and electron microscopic evidence of neuroectodermal differentiation. "In Ewing’s sarcoma, RPSAP52 was generally lowly expressed with the exception of A673 cell line." (PMID 31484926, 2019).
pituitary adenomas (2 papers, 2025 to 2026). "RPSAP52 (Ribosomal Protein SA Pseudogene 52) is an antisense lncRNA for the HMGA2 gene, with an overexpression that is critical in developing pituitary adenomas." (PMID 40362297, 2025).
rhabdomyosarcoma (2 papers, 2019 to 2021). A rare aggressive malignant mesenchymal neoplasm arising from skeletal muscle. "Both RPSAP52 isoforms were abundantly expressed in most rhabdomyosarcoma cell lines, with just one order of magnitude higher HMGA2 expression in Rh28, Rh41, or CW9019 cells." (PMID 31484926, 2019).
type 2 diabetes (2 papers, 2019 to 2023). "The gene closest to the CBCT− top hit, cg07677157, is RPSAP52, a gene linked to type 2 diabetes in genome-wide association studies (GWAS)." (PMID 31796056, 2019).
adrenocortical carcinoma (1 paper, 2019). "The analysis of the collection of human cancers available from The Cancer Genome Atlas (TCGA) indicates HMGA2 and RPSAP52 expression is specially increased in adrenocortical carcinoma, mesothelioma and in the sarcoma samples available (as measured by Z-score)." (PMID 31484926, 2019).
Alzheimer disease (1 paper, 2022). A progressive, neurodegenerative disease characterized by loss of function and death of nerve cells in several areas of the brain leading to loss of cognitive function such as memory and language. "The polymorphisms within the RPSAP52 gene were associated with schizophrenia in founder populations and associated with biomarkers of Alzheimer’s disease, such as cerebrospinal fluid beta-amyloid 1–42 levels." (PMID 36137074, 2022).
anxiety disorder (1 paper, 2025). A category of psychiatric disorders which are characterized by anxious feelings or fear often accompanied by physical symptoms associated with anxiety. "Interestingly, the RPSAP52, SLC47A2, SH3RF3 genes have also been implied in a previous cross-anxiety disorder EWAS." (PMID 40281224, 2025).
Cognitive impairment (1 paper, 2022). Abnormal cognition is characterized by deficits in thinking, reasoning, or remembering. "In particular, Ribosomal Protein SA Pseudogene 52 (RPSAP52) is associated with brain structure variations in TWAS and described in genetic investigations of cognitive impairment, neurodevelopmental and neurodegenerative disorders." (PMID 36137074, 2022).
colorectal cancer (1 paper, 2022). A primary or metastatic malignant neoplasm that affects the colon or rectum. "This interplay between HuR, the lncRNA RPSAP52 (Ribosomal Protein SA Pseudogene 52) and miRNA-dependent regulation has been associated with the regulation of the cell cycle inhibitor, p21, in colorectal cancer cells (HT-29)." (PMID 35884580, 2022).
diabetic retinopathy (1 paper, 2022). "LncRNA RPSAP52 is reported to repress cell apoptosis in diabetic retinopathy." (PMID 35322746, 2022).
pituitary cancer (1 paper, 2021). A primary or metastatic malignant neoplasm affecting the pituitary gland. "D'Angelo et al31 found that RPSAP52 was up‐regulated in pituitary cancers and induced cell growth through sponging HMGA." (PMID 33787061, 2021).
sarcoma (1 paper, 2019). A usually aggressive malignant neoplasm of the soft tissue or bone. "TCGA RNA expression and DNA methylation data showed that RPSAP52 promoter hypermethylation was associated with transcript downregulation across sarcoma samples (Pearson correlation, r2 = 0.264, P-value = 4.764e–10)." (PMID 31484926, 2019). "In addition, high levels of RPSAP52 in patient samples associate with a worse prognosis in sarcomas." (PMID 31484926, 2019).
cancer (7 papers, 2015 to 2024). A tumor composed of atypical neoplastic, often pleomorphic cells that invade other tissues. "Finally, a set of recently discovered cancer-associated lncRNAs, namely RPSAP52 (Ribosomal protein SA pseudogene 52), LINC00941, and LINC02577 were identified." (PMID 38612755, 2024). "Consistent with their convergent roles in the same pathway, low expression of HMGA2/RPSAP52 in differentiated cells and reexpression in cancer mirrors LIN28 levels, which is one of the key players in maintenance of the pluripotent state." (PMID 31484926, 2019). "NANOG and OCT4 protein levels were decreased in RPSAP52-depleted cells, suggesting this lncRNA promotes features of cancer stem cells." (PMID 31484926, 2019). "Conversely, downregulation of HMGA2 protein and decreased proliferation rate of cancer cells were observed when RPSAP52 expression was inhibited by antisense oligonucleotides." (PMID 26137461, 2015). "lncRNA RPSAP52 exerted anti-cancer effects via regulating miR-665/STAT3 in GC." (PMID 35322746, 2022). "While, more biological functions of LncRNA RPSAP52 remain to be researched in cancer." (PMID 35322746, 2022). "LncRNA RPSAP52 exerted anti-cancer effects via modulating miR-665/STAT3 in GC." (PMID 35322746, 2022). "Remarkably, lncRNA RPSAP52 depletion also exerted anti-cancer effects in vivo." (PMID 35322746, 2022). "RPSAP52 thus displays characteristics of an oncogenic gene whose dysregulation might contribute to the progression of a number of human cancers." (PMID 31484926, 2019). "We next attempted to determine whether RPSAP52-mediated regulation of proliferative pathways occurred in other cancer types." (PMID 31484926, 2019). "The expression level of RPSAP52 is positively correlated with TGF-β1, leading to its upregulation, while silencing of RPSAP52 leads to a decrease in CD133+ cells, which seem to describe the phenotype of cancer-initiating cells." (PMID 34947885, 2021). "Regarding pseudogenes, the downregulation of transcribed pseudogene RPSAP52 enhances the oncofetal HMGA2-IGF2BP2-RAS axis through impairing the balance between the oncogene LIN28B and tumor suppressor let-7 in human cancers." (PMID 33027767, 2020). "Recent results demonstrate that the enforced expression of RPSAP52 is able to increase the HMGA2 protein level, induces cancer cell proliferation, and promotes cell cycle progression." (PMID 26137461, 2015).
tumor (6 papers, 2017 to 2023). "LncRNA RPSAP52 depletion induced tumor necrosis and reduced the level Ki-67 which is a cell proliferation marker." (PMID 35322746, 2022). "Our results revealed that decreased tumor weight and volume were found following lncRNA RPSAP52 depletion." (PMID 35322746, 2022). "This intricate network of reciprocal regulation is further complicated by the observation in tumor cells that RPSAP52, a non-coding RNA (ncRNA) transcribed from a ribosomal protein pseudogene, has an apparently important role in the network." (PMID 31935816, 2020). "MCF10A and Hs578T cells stably expressing either scrambled shRNAs or shRNAs against RPSAP52 were subcutaneously injected into mice, and the tumor formation and volume was monitored." (PMID 31484926, 2019). "In an in vivo setting, and similarly to the observations in breast cell lines, this results in a marked reduction in tumor formation when mice are subcutaneously injected with RPSAP52-depleted A673 cells." (PMID 31484926, 2019). "Taken as a whole, RPSAP52 is a pseudogene with an important impact on a major tumor suppressor miRNA." (PMID 31484926, 2019). "RT-PCR followed by Sanger sequencing verified the presence of the RPSAP52-XR_044195 fusion transcript in the tumor." (PMID 28591699, 2017). "Tumor growth in vivo was suppressed following lncRNA RPSAP52 depletion." (PMID 35322746, 2022). "RPSAP52 is a pseudo gene and was fused to LNCKB.11978 in tumor TCGA-DX-AB2S." (PMID 37638762, 2023). "Upon engrafting mice, both mut-ZDHHC17-LNCKB.11978 and RPSAP52-LNCKB.11978 promoted in vivo tumor growth, although not reaching statistical significance due to large variations in animal experiments." (PMID 37638762, 2023). "Histopathological analysis demonstrated that tumor necrosis was found in the tumor tissue after lncRNA RPSAP52 knockdown, while no obvious pathological lesion change was found in tumor tissue of control group." (PMID 35322746, 2022). "Notably, downregulation of RPSAP52 impairs the balance between the oncogene LIN28B and the tumor suppressor let-7 family of miRNAs, inhibits cellular proliferation and migration in vitro and slows down tumor growth in vivo." (PMID 31484926, 2019). "RPSAP52 was overexpressed in 25 TSCC cases (25/30, 83.3%) compared with control no‐tumour samples." (PMID 33787061, 2021).
RPSAP52 also shares sentences with these, for which no sentence is quoted: breast carcinoma (4 papers); mesothelioma (1); schizophrenia (1); tongue squamous cell carcinoma (1).